PICK1 (protein interacting with PRKCA 1)
Description:
Probable adapter protein that bind to and organize the subcellular localization of a variety of membrane proteins containing some PDZ recognition sequence. Involved in the clustering of various receptors, possibly by acting at the receptor internalization level. Plays a role in synaptic plasticity by regulating the trafficking and internalization of AMPA receptors. May be regulated upon PRKCA activation. May regulate ASIC1/ASIC3 channel. Regulates actin polymerization by inhibiting the actin-nucleating activity of the Arp2/3 complex; the function is competitive with nucleation promoting factors and is linked to neuronal morphology regulation and AMPA receptor (AMPAR) endocytosis. Via interaction with the Arp2/3 complex involved in regulation of synaptic plasicity of excitatory synapses and required for spine shrinkage during long-term depression (LTD). Involved in regulation of astrocyte morphology, antagonistic to Arp2/3 complex activator WASL/N-WASP function.
Synonyms: PRKCABP; dJ1039K5; MGC15204; PICK
Tractability: Small molecule: a structure with a bound ligand is known. Antibody: its Gene Ontology location is reachable by antibodies, with high confidence; UniProt places it where antibodies can reach, with medium confidence. PROTAC: ubiquitination databases record sites on it; its protein half-life has been measured.
Safety:
Unwanted effects reported when the protein is acted on. In parentheses: how it was acted on, where the effect was seen, and who reports it.
not studied (source: ClinPGx)
spontaneous relapse of psychosis (source: ClinPGx)
Gene: Protein-coding gene on chromosome 22 (38,056,311 to 38,075,719, forward strand). Ensembl gene ENSG00000100151.
Subcellular location: Cytoplasm, perinuclear region; Membrane; Postsynaptic density; Synapse, synaptosome; Cytoplasm, cytoskeleton
Subcellular location (Human Protein Atlas): Cytosol
Pathways (Reactome):
Hemostasis: Cell surface interactions at the vascular wall
Neuronal System: Trafficking of GluR2-containing AMPA receptors
Gene Ontology:
Molecular function: identical protein binding; membrane curvature sensor activity; protein binding; actin filament binding; Arp2/3 complex binding; G protein-coupled receptor binding; phospholipid binding; protein domain specific binding; protein kinase C binding; signaling receptor binding
Biological process: regulation of insulin secretion; cellular response to decreased oxygen levels; cellular response to glucose starvation; dendritic spine maintenance; dendritic spine organization; glial cell development; intracellular protein transport; long-term synaptic depression; negative regulation of Arp2/3 complex-mediated actin nucleation; neuronal ion channel clustering; positive regulation of receptor internalization; protein phosphorylation; receptor clustering; regulation of Arp2/3 complex-mediated actin nucleation
Cellular component: cytoplasm; cytosol; plasma membrane; presynaptic membrane; endocytic vesicle membrane; Golgi apparatus; membrane; neuron projection; perinuclear region of cytoplasm; postsynaptic density; synapse; synaptic vesicle; trans-Golgi network membrane; cytoskeleton
Genetic constraint (gnomAD): Loss-of-function variants: 24 observed, 43.81 expected, observed/expected ratio (o/e) 0.55, 90% interval 0.4 to 0.77. The upper end of that interval is the gene's LOEUF score, 0.77, which puts it in group 3 of 6, group 1 being the genes least tolerant of losing a copy. Missense variants: 418 observed, 555.67 expected, observed/expected ratio (o/e) 0.75, 90% interval 0.69 to 0.82. Synonymous variants: 214 observed, 230.29 expected, observed/expected ratio (o/e) 0.93, 90% interval 0.83 to 1.04.
Homologues: Orthologues: macaque PICK1 (100% identical), chimpanzee PICK1 (99% identical), dog PICK1 (98% identical), rat Pick1 (97% identical), mouse Pick1 (96% identical), pig PICK1 (95% identical), guinea pig PICK1 (95% identical), zebrafish pick1 (80% identical), tropical clawed frog pick1 (76% identical), rabbit PICK1 (65% identical), Drosophila melanogaster PICK1 (56% identical), Caenorhabditis elegans Y57G11C.22 (46% identical). Paralogues in human: ARFIP2 (21% identical), ARFIP1 (19% identical).
Diseases named in the same sentence as PICK1 in open-access papers:
PICK1 is named in the same sentence as 69 diseases in open-access papers, as found by Europe PMC text mining. Sharing a sentence is not in itself a finding about the gene and the disease. The quoted sentences say what the papers report.
Globozoospermia (15 papers, 2016 to 2025). Any structural anomaly of the acrosome resulting in a round sperm head. "Human genes thathave been largely associated with globozoospermia include proteins interactingwith C kinase 1 (PICK1), SPATA16, zonapellucida binding protein 1 (ZPBP1), and Dpy-19-like-2(DPY19L2)." (PMID 40833973, 2025). "Regarding the other globozoospermia-associated gene, PICK1 seems to be crucial for acrosome biogenesis and a homozygous missense mutation in exon 13 of this gene resulted in round-headed acrosomeless spermatozoa in one member of a Chinese family." (PMID 34209343, 2021). "Our genetic analysis of 3 CG men confirmed a deletion of 3 genes—DPY19L2, SPATA16, and PICK1—which are often associated with the globozoospermia phenotype and contribute to the most relevant feature of this condition, the absence of acrosome." (PMID 33877510, 2021). "For example, protein interacting with PRKCA 1 (PICK1) is regularly mentioned as a gene that causes globozoospermia in human patients." (PMID 30865283, 2019). "In gene KO mouse studies, various genes (Atg7, Csnk2a2, Dpy19l2, Gba2, Golga2, Gopc, Hrb, Hsp90b1, Mfsd14a, Pick1, Sirt1, Slc9a8, Smap2, Spaca1, Tmf1, Vps54, Zpbp1) were found to be associated with globozoospermia." (PMID 29065458, 2017). "Researchers have recently identified a large deletion, about 200 kbp,encompassing the whole length of DPY19L2 or mutations in SPATA16 and PICK1 genesassociated with globozoospermia." (PMID 27441053, 2016). "Regarding the other genes, in the present study mutation screening of the SPATA16 and PICK1 genes were also carried out on 27 cases with globozoospermia and 30 fertile men." (PMID 27441053, 2016). "This autosomal recessive genetic mutation in PICK1 was responsible for globozoospermia in humans." (PMID 29065458, 2017). "Defects in the interacting proteins Gopc and Pick1 impair the transport of Golgi vesicles to the acrosome and their recycling, leading to globozoospermia." (PMID 39680136, 2024). "Protein interacting with PRKCA 1 (PICK1) is necessary for cytoskeletal organization and acrosome formation, and its deletion leads to globozoospermia." (PMID 34041237, 2021). "The most common abnormality is variation in the DPY19L2 gene, while variations in the SPATA16, PICK1 and GGN have also been investigated as causes of globozoospermia." (PMID 34361119, 2021). "Analyzing the reported percentage of DPY19L2 mutations, together with those of the two other globozoospermia-associated genes SPATA16 and PICK1, more than half of the cases carried DPY19L2 mutations, with a rather lower frequency of SPATA16 or PICK1 mutations." (PMID 34209343, 2021). "A subset of genetic mutations, such as DNAH6, SPATA16, DPY19L2, PICK1, and CCIN related to globozoospermia, have been reported in the past few years." (PMID 32582379, 2020). "Next, the onset of Spata16 expression was examined by RT-PCR and compared with that of globozoospermia-related genes: Dpy19l2, Pick1, and Spaca1." (PMID 29065458, 2017). "In conclusion, according to the evidence reported so far, besides DPY19L2, other genes that might be confidently associated with globozoospermia in humans, and whose analysis might be recommended in clinical practice, are SPATA16, PICK1, ZPBP1, and CCDC62." (PMID 38790229, 2024). "Therefore, the aim of our study was to investigate the genetic contribution of the main globozoospermia-associated genes (SPATA16, PICK1 and DPY19L2) in 18 unrelated Italian men." (PMID 34209343, 2021). "CCDC62 contains coiled-coil domains similar to PICK1 and GOPC, whose knockout mouse models display also globozoospermia." (PMID 31985809, 2020). "Only, four genes have been so far detected in individuals presenting globozoospermia including DPY19L2, SPATA16, PICK1 and Calicin." (PMID 30291685, 2019). "Knockout mice approach for different purposewhich later exhibited globozoospermia manifestation.The target genes were as: Csnk2a2, GOPC, Gba2,PICK1, iii." (PMID 30291685, 2019).
Globozoospermia (continued). "Although Pick1 gene knockout (KO) mice were viable and showed no gross developmental defects, KO males were infertile with abnormal sperm heads reminiscent of globozoospermia." (PMID 29065458, 2017). "However, the genetic assessment failed to include additional genes associated with globozoospermia, such as SPATA16 and PICK1." (PMID 33877510, 2021).
breast carcinoma (14 papers, 2014 to 2025). "Experimental evidence suggests that PICK1 is involved in promoting tumor growth and is associated with poor prognosis in human breast cancer." (PMID 36408514, 2022). "It will be interesting to demonstrate if Ago2 is implicated in miR-615-3p-mediated PICK1 repression in breast cancer cells." (PMID 32336285, 2020). "Among the shortening transcripts in Vim KO breast cancer cells, the APA event observed in the 3′‐UTR of Pick1 gene is one of the most significant events and associated with the EMT process." (PMID 39781570, 2025). "Based on DANPOS results, the distal polyadenylation site (PAS) of Pick1 is mainly used in WT breast cancer cells while the usage of proximal PAS is significantly increased in Vim KO breast cancer cells." (PMID 39781570, 2025). "We next focused on elucidating the influence of miR‐615‐3p on breast cancer progression through its interaction with PICK1." (PMID 39781570, 2025). "GLI3 and PICK1 were found to over-express in various cancers, including colorectal cancer, ovarian cancer, breast cancer, prostate cancer, and oral squamous cell carcinoma." (PMID 38280969, 2024). "Lei found that miR-615-3p acts as an oncogenic factor that promotes EMT and metastasis in breast cancer by regulating the PICK1/TGFBRI axis." (PMID 37394466, 2023). "PICK1 inhibits the processing of pre-mir-615-3p to mature miR-615-3p via interfering with the binding of DICER1 to Smad2/3 in breast cancer cells." (PMID 35183226, 2022). "PICK1 was also involved in breast cancer by inhibiting TGF-β signaling, thus initiating early cancer." (PMID 34307672, 2021). "Despite multiple relationships, our data provide solid evidence that the miR-615-3p/PICK1 axis has an important role in breast cancer cell migration and invasion." (PMID 32336285, 2020). "We next examined the clinical relevance of altered miR-615-3p and PICK1 expression in human breast cancers." (PMID 32336285, 2020). "In summary, our data strongly suggest that concurrent gain of miR-615-3p and loss of PICK1 expression may be an important step in breast tumor progression and metastasis, highlighting the potential role of miR-615-3p in the prognostic evaluation and therapeutic application for breast cancers." (PMID 32336285, 2020). "The consistency seen in the in vivo model and the excellent correlation between PICK1 expression and survival of patients with breast cancer in breast tumors supports the role of PICK1 in breast tumorigenicity established by our experimental studies." (PMID 32336285, 2020). "We postulated that one signal axis such as miR-615-3p/PICK1 has a critical role in specific cellular signaling and its function in breast cancer depends on the genetic context." (PMID 32336285, 2020). "We also investigated the relationship between miR-615-3p expression and the mRNA and protein levels of PICK1 in breast cancer patients." (PMID 32336285, 2020). "The knockdown of PICK1 confers epithelial-like breast cancer cells with the ability to invade Matrigel and to disseminate." (PMID 32336285, 2020). "What is more, PICK1 participates in the breast cancer though inhibiting TGF-β signaling thus initiating the early cancer." (PMID 30402043, 2018). "We discovered an upregulation of PICK1 in VIM‐KO breast cancer cells, suggesting a novel regulatory mechanism whereby VIM may control breast cancer progression through the miR‐615‐3p/PICK1 axis." (PMID 39781570, 2025). "Especially, it was also suggested that PICK1 may participate in breast cancer development by targeting TGF-β type I receptor (TβRI) for degradation." (PMID 32336285, 2020). "However, we found that PICK1 is hardly detectable in breast cancer tissue but exhibits a higher level in normal breast tissue." (PMID 32336285, 2020). "suggesting that miR-615-3p promotes the malignant phenotypes of breast cancer by targeting PICK1." (PMID 32336285, 2020). "Additionally, the downregulation of PICK1 promotes the metastasis of breast cancer cells." (PMID 38664379, 2024).
breast carcinoma (continued). "Indeed, PICK1 has an important role in breast cancer and other cancer initiation." (PMID 32336285, 2020). "Utilizing the 4T1 breast cancer cell model, we first used RNA‐seq and proteomics to investigate the changes in the APA of PICK1 following VIM knockout (KO)." (PMID 39781570, 2025). "RNA‐seq and proteomic profiling revealed significant APA in PICK1 following VIM KO, suggesting a novel mechanism by which VIM regulates breast cancer progression." (PMID 39781570, 2025). "According to their study, miR‐615‐3p facilitates breast cancer metastasis by directly targeting the 3′‐UTR of PICK1 mRNA, leading to reduced PICK1 expression, which in turn influences TGF‐β signaling and its downstream effects on cell migration and invasion." (PMID 39781570, 2025). "Herein, we assess the role of PICK1 on the TGF-β signaling effectors SMAD2/3 and DICER1 in the processing of pre-miR-615-3p to yield mature miR-615-3p in breast cancer cells." (PMID 32336285, 2020). "MiR-615-3p contributed to epithelial-to-mesenchymal transition and metastasis in breast cancer by regulating a negative feedback loop involving the PICK1/TGFBRI axis." (PMID 37508580, 2023). "We found that the levels of the PICK1 mRNA were lower in breast cancer tissues than in non-cancerous tissues and correlated with lymphatic metastasis and the histological grade of the tumor." (PMID 32336285, 2020). "Moreover, in breast cancer tissues and breast cancer cell lines, miR-615-3p level is also upregulated, and promotes metastatic ability by targeting 3’-UTR of PICK1, inhibiting it, and thus increasing TGF-β signaling." (PMID 32605009, 2020). "We measured PICK1 protein levels in human breast cancer and matched non-cancerous tissues using immunohistochemical staining." (PMID 32336285, 2020). "Indeed, we observed a significant negative correlation between PICK1 expression and TβRI or phospho-Smad2 levels in human breast tumors, indicating that PICK1 may be involved in breast cancer development through inhibition of TGF-β signaling." (PMID 25332839, 2014). "Together, our data suggest that PICK1 inhibits the binding of DICER1 to Smad2/3 and the processing of pre-miR-615-3p to mature miR-615-3p in breast cancer cells, thus exerting a negative feedback loop." (PMID 32336285, 2020). "In turn, PICK1 inhibits the binding of DICER1 to Smad2/3 and the processing of pre-miR-615-3p to mature miR-615-3p in breast cancer cells, thus exerting a negative feedback loop." (PMID 32336285, 2020). "PICK1 inhibits the binding of DICER1 to Smad2/3 and the processing of pre-miR-615-3p to mature miR-615-3p in breast cancer cells, thus exerting a negative feedback loop." (PMID 32336285, 2020).
male infertility (10 papers, 2010 to 2024). The inability of the male to effect fertilization of an ovum after a specified period of unprotected intercourse. "Next, to address putative on-target side effects, we tested the effect of repeated administration of mPD5 (s.c., 10 μmol/kg, once daily for 14 days) versus vehicle on male fertility, since complete loss of PICK1 is known to cause male infertility." (PMID 39287978, 2024). "In general, for the first time, we attribute male infertility caused by PICK1 deficiency to impaired vesicle trafficking function of Sertoli cells to provide a key scientific basis for the precise diagnosis and treatment of male infertility." (PMID 38001535, 2023). "PICK1 also regulates vesicle trafficking between Golgi and acrosome in spermatids and deficiency of PICK1 in mice leads to abnormal acrosome formation and male infertility." (PMID 21176140, 2010). "Our study attributed male infertility caused by PICK1 deficiency to impaired vesicle-related secretory function of Sertoli cells and identified a variety of significant candidate biomarkers for male infertility induced by PICK1 deficiency." (PMID 38001535, 2023). "In our study, D-(-)-glutamine, vitamin B12, meaquinone (vitamin K2), and beta-estradiol 17-acetate could serve as metabolic biomarkers for male infertility caused by PICK1 deletion." (PMID 38001535, 2023). "Besides, deficiency of PICK1 would cause male infertility in patients and animals as PICK1 is essential for vesicle trafficking from the Golgi apparatus to the acrosome in sperm cells." (PMID 30402043, 2018). "Our previous work found that PICK1 is involved in the trafficking of proacrosomal granules, a type of dense core vesicle in the spermatocytes, and PICK1 deficiency in mice leads to abnormal acrosome formation in sperm and male infertility." (PMID 23630453, 2013). "PICK1, the protein interacting with C kinase 1, plays an important role in Golgi-derived vesicle trafficking, and its deficiency in the male reproductive system results in abnormal vesicle trafficking from Golgi to acrosome, which eventually disrupts acrosome formation and leads to male infertility." (PMID 37551344, 2023). "The secretion of inhibin B in male infertility patients and subsequent enrichment analysis of biological function suggested that PICK1 deficiency may affect the differentiation and maturation of sperm by destroying the vesicle trafficking of Sertoli cells, thus leading to male infertility." (PMID 38001535, 2023). "To explore the relationship between PICK1 and explicit male infertility genes, we constructed a PICK1-centered PPI interaction network." (PMID 38001535, 2023). "Male infertility: PICK1 homozygous KO males are infertile, whereas heterozygotes demonstrate fertility comparable to wild-type mice." (PMID 35455935, 2022). "Several genetic mutations, including PRM1, AURKC, SPATA16, PICK1, DPY19L2, SEPT12, and SEPT14, result in male infertility and are caused by sperm DNA damage in a clinical context." (PMID 36295569, 2022). "Based on integrated multi-omics analysis, we identified a variety of significantly differentially expressed molecules that could be candidate biomarkers for male infertility induced by PICK1 deletion." (PMID 38001535, 2023). "Taken together, this data implicates PICK1 in male infertility, whereas a phenotype for female mice has not been reported." (PMID 35455935, 2022).